EGFR (epidermal growth factor receptor)
Diseases named in the same sentence as EGFR in open-access papers (continued):
Sharing a sentence is not in itself a finding about the gene and the disease.
tumor (continued). "Our results showed that EGFR positive expression was an independent prognostic factor for NSCLC, among various factors including patient's age, gender, histopathology, tumor differentiation, tumor size, TNM staging and chemotherapy/radiotherapy." (PMID 21385353, 2011). "To determine molecular subtypes we characterized over 200 tumor specimens obtained from Egypt by performing ER, PR, Her2, CK5/6, EGFR and Ki67 immunohistochemistry." (PMID 21961708, 2011). "In the current study, we analyzed the efficacy and toxicity of a 2nd EGFR-TKI treatment in patients who demonstrated a response to prior gefitinib therapy and tumor progression." (PMID 21194487, 2011). "Experimental mouse models suggest that EGFR is important for tumor cell motility and invasion, and HER2 for tumor cell intravasation." (PMID 21914172, 2011). "Male Apcmin/+ mice with an intestinal tumour burden were exposed to a single dose of an inhibitor against EGFR (gefitinib), IGF1R (AZ12253801), 0.5% Tween 80 or combined EGFR/IGF1R inhibitor and culled 4 h post dosing." (PMID 21811251, 2011). "These biomarkers primarily focus on target biomarkers in tumours that predict patient response, although, more recently, tumour biomarkers of resistance have also been employed, as with mutant KRAS in EGFR-directed therapies." (PMID 21649578, 2011). "Based on these findings, the European Medicines Agency and the US Food and Drug administration have placed restrictions on the usage of EGFR-targeted drugs and only approved for CRC metastatic patients with wild-type KRAS tumours." (PMID 21673680, 2011). "In addition, since the EGFR is over-expressed in several highly resistant tumor entities and restoration of chemosensitivity might have a significant therapeutic impact, we evaluated the effects of gefitinib as a commercially available EGFR inhibitor on the drug-resistance phenotype." (PMID 22088142, 2011). "In this paper, the authors concluded that the inhibition of EGFR expression combined with the effects of PDT strongly favored apoptosis and enhanced anti-tumor activity." (PMID 24212824, 2011). "In different tumor models, MUC1 was shown to regulate cell proliferation by interacting with several proteins such as ER-α, β-catenin and EGFR." (PMID 22073229, 2011). "HPV-negative tumours tend to express significantly more pEGFR than HPV-positive cancers and this expression correlates with pAkt protein, indicating EGFR as an upstream regulator of Akt signalling in PSCC." (PMID 21407808, 2011). "C225-NP exhibited a strong and selective antitumor effect on EGFR-expressing NSCLC cells by inhibiting EGFR-mediated signal transduction and induced autophagy and apoptosis in tumor cells." (PMID 22087216, 2011). "Therefore, it is well expected that mutual blockade through therapies directed against both endothelial cells and tumor cells may affect CSC-mediated tumor growth by disrupting the vascular endothelial microenvironment, in addition to abrogate the EGFR-mediated activation on these cells." (PMID 24212957, 2011). "The results showed the protein levels of EGFR and AKT were decreased in the tumor homogenates in both curcumin alone and curcumin combined with gefitinib groups, whereas, the c-MET, cyclin D1, and PCNA were also down-regulated simultaneously." (PMID 21858220, 2011). "High cPLA2α mRNA expression correlated with clinical parameters of poor prognosis, which are characteristic of highly invasive tumours of the HER2-positive and basal-like subtype, including low oestrogen receptor expression and high EGFR expression." (PMID 21119660, 2011). "Fluorescent in situ hybridisation analyses of PTEN, PIK3CA, EGFR and CEN7 were performed on tumour specimens from patients treated on the expanded access gefitinib trial." (PMID 22095222, 2011).
tumor (continued). "Significant correlations were observed between protein expression of Raf-1 and MAPK with the type 1 receptor tyrosine kinases, Her2 and epidermal growth factor receptor, as well as the transcription factor AP-1 in CRPC tumours." (PMID 21559022, 2011). "A major signaling route of EGFR is the mitogen-activated protein kinases (MAPK) pathway and its overactivation plays a critical role in tumor development and progression." (PMID 22185378, 2011). "Aberrant overexpression, activation, and dimerization of the individual members of the HER family--comprised of EGFR (Epidermal Growth Factor Receptor 1)/HER1, HER2, HER3, and HER4--contribute both to aggressive tumor growth and poor patient prognosis." (PMID 21884573, 2011). "Epidermal growth factor receptor is widely accepted as a crucial signalling platform on which growth factor signals converge, and the effect of its overexpression in HNSCC tumours has been described extensively." (PMID 21102583, 2011). "In a hypothesis-generating retrospective analysis of tumour biopsy samples of 113 patients treated with anti-EGFR moAb plus chemotherapy, BRAF-mutated patients did not respond to therapy and had a shorter progession-free survival and overall survival (OS) compared with BRAF wild-type patients." (PMID 20234366, 2010). "On average 3.89 (+/- 1.12) signals for the 7p12 EGFR locus and 3.12 (+/- 0.82) CEP 7 signals were detected within the tumor cells." (PMID 20196851, 2010). "Preclinical studies suggest that the Epidermal Growth Factor Receptor (EGFR), HER2, and their pathways have a crucial role in tumor growth." (PMID 21087480, 2010). "After one week, half of the mice of each experimental group (Mock, EGFR-L858R and TGFα) received doxycycline to silence MET in the tumor." (PMID 20500904, 2010). "Chen and colleagues generated FX-derived, Gla domain scFv-fusion proteins directed against the tumor targets HER2 and EGFR, or towards the stem cell marker, ATP-binding cassette protein G2 (ABCG2)." (PMID 21994621, 2010). "Along with traditional markers such as FABP5, epidermal growth factor receptor, E-cadherin, CD74, and CD24, newly published biomarkers for the staining of HNSCC primary tumor biopsies include IL13Rα2, CD44v6, and the stem cell marker CD133." (PMID 20175927, 2010). "It has been studied that after irradiation the expression of EGFR and TGF-α increased which enhanced the ability of the tumor cells to repair DNA damage, and rapidly proliferate." (PMID 20969791, 2010). "As EGFR and VEGFR expressions were shown to be important for NSCLC cancer, there is significant rationale behind the treatment of these tumours with BMS-690514." (PMID 20628392, 2010). "Erlotinib, an EGFR TKI, is an effective anti-tumor agent for treatment of NSCLC among elderly patients." (PMID 21194444, 2010). "Lacking standard chemotherapy treatment options for this rare tumor type, subsequent pathology review indicated +2 EGFR expression (Zymed assay) and a 6-week trial of the epidermal growth factor receptor (EGFR) inhibitor erlotinib was initiated." (PMID 20696054, 2010). "EGFR family members EGFR and HER2 are overexpressed in many cancers and are integral to tumor progression, in part due to their ability to stimulate release of angiogenic factors including VEGF." (PMID 20628489, 2010). "In patients with HER2-positive tumours receiving the epidermal growth factor receptor (EGFR)/HER2 inhibitor lapatinib in an adjuvant setting, a decrease in CD44+/CD24−/low cells and tumour mammosphere-forming efficiency was observed." (PMID 20145614, 2010). "Similar to the CTCs isolated from NSCLC patients, we were able to detect EGFR, pEGFR, HER2, and pHER using IF in the CTCs and the frequency of staining was less than in the SKBR3 tumour cell line." (PMID 20461092, 2010). "Cooperative signaling between EGFR and TGF-β regulates tumor invasion, neo-angiogenesis and inflammation." (PMID 20428086, 2010).
tumor (continued). "Vandetanib (formerly known as ZD6474) inhibits two key pathways in tumor growth: VEGFR-dependent tumor angiogenesis, and EGFR-dependent tumor cell proliferation and survival." (PMID 21050422, 2010). "Previous work carried out in transgenic EGFR and ERBB2-mutant mice showed substantial tumor regression when mice were treated with a combination of BIBW-2992 and rapamycin targeting mTOR (or more specifically TORC1)." (PMID 20111714, 2010). "Tumor-bearing animals were treated with a VEGFR 2 and EGFR inhibitor: ZD6474 (Astra Zeneca), and authors compared short-term effects of this treatment (after three days) with those induced by castration." (PMID 27713352, 2010). "A combined therapy targeting IGF1R and EGFR was shown to successfully inhibit tumour cells, which were resistant to IGF1R blockage by overexpressing the EGFR pathway." (PMID 20924377, 2010). "In our anti-angiogenesis study, we demonstrated that combination of EGFR targeted antibody, Erbitux with PDT strongly inhibited tumor growth in the bladder tumor xenograft model." (PMID 27713315, 2010). "This compound inhibits two key pathways in tumor growth: VEGFR-dependent tumor angiogenesis and EGFR-dependent tumor cell proliferation and survival." (PMID 20433767, 2010). "The anti-angiogenic effect of EGFR targeting was demonstrated for Acm and TKI, in particular by inhibition of tumor secretion of pro-angiogenic factors such as VEGF and factor VIII." (PMID 27713352, 2010). "Frozen tumor specimens of 83 NSCLC patients from various ways had been included, after DNA extraction and polymerase chain reaction (PCR) on EGFR exon 19 and 21, the results from the direct sequencing and DHPLC were compared." (PMID 20840812, 2010). "Mean tumor number in the group using both the HGF neutralizing antibody L2G7 and the EGFR inhibitor gefitinib was significantly lower than with single agents." (PMID 21390244, 2010). "Despite the blockade of PI3K, EGFR and mTOR with efficient AKT inhibition, little apoptosis of the tumour cells was detected, again emphasizing the need to induce cytotoxic rather than cytostatic therapeutic responses." (PMID 20515495, 2010). "In all, 28% of all patients showed coexpression of both pathways in terms of EGFR, p-mTOR and p-p70s6K positivity in SCLC tumour specimens." (PMID 20683448, 2010). "Given the importance of EGFR-mediated signalling in NSCLC, various EGFR pathway-related proteins have already been studied as potential markers using IHC in NSCLC tumour samples." (PMID 19050706, 2009). "Three of these potential targets are EGFR, PDGFR and VEGFR2, which have important roles in tumour proliferation and angiogenesis." (PMID 19563658, 2009). "Among EGFR inhibitors, nimotuzumab (TheraCIM h-R3) and cetuximab (IMC-C225) have undergone an extensive evaluation in different tumour locations, showing activity when administered with ionising radiation." (PMID 19293809, 2009). "The basal EGFR expression in healthy control rats (BH, n = 10) was 5.1±0.2 fmol/ml (mean ± SEM) and it increased in tumor-induced rats (BT, n = 7) to 6.9±0.6 fmol/ml (P < 0.01)." (PMID 19491505, 2009). "Tumour phenotypes were established as described in Cheang and colleagues by expression analysis of five biomarkers, ER, PR, HER-2, EGFR and CK5/6 on TMA sections." (PMID 19589159, 2009). "To better understand the influence of the EGFR blockade on radiation response in GBM, we investigated the antitumour effect of combined treatment with two mAb to EGFR and radiation in human tumour U87MG xenografts." (PMID 19293809, 2009).
tumor (continued). "Indeed, one may envision that tumours relying heavily on EGFR signalling will tend to express ligands that do not induce EGFR degradation, and that these tumours therefore will be more sensitive to EGFR-targeted treatment." (PMID 19531065, 2009). "One tumor had both Ink4a/ARF region deletion and EGFR amplification, however total and phosphorylated EGFR levels in this tumor were low and PDGFB was present." (PMID 19915670, 2009). "Previous research has shown overexpression of epidermal growth factor receptor (EGFR) on most MM cell lines and clinical tumour samples." (PMID 19755995, 2009). "Vandetanib (ZACTIMATM) is a once-daily oral anticancer drug that selectively targets VEGFR-dependent tumor angiogenesis and REarranged during Transfection (RET)- and epidermal growth factor receptor (EGFR)-dependent tumor cell proliferation and survival." (PMID 19946413, 2009). "The tumor promoters OA and menadione downregulated the expression of CCHCR1, Ki67, and EGFR mRNAs in HaCaT cells." (PMID 19551138, 2009). "The epidermal growth factor receptor (EGFR) pathway plays a fundamental role in the carcinogenesis and progression of various tumour types, including NSCLC." (PMID 19050706, 2009). "Conversely, pharmacological inhibition of EGFR can decrease VEGF expression and consequently angiogenesis in many tumor types." (PMID 19657384, 2009). "Many basal-like tumours express cytokeratins (CK) 5, 6 and 17 as well as HER1 (epidermal growth factor receptor (EGFR)." (PMID 19320967, 2009). "Reconstruction experiments were used to optimise immunomagnetic enrichment and RT-PCR detection of circulating tumor cells using four markers (ELF3, CK19, EGFR and EphB4)." (PMID 19961621, 2009). "Epidermal growth factor receptor and VEGF protein expressions were also confirmed by IHC in xenograft tumours." (PMID 19319137, 2009). "Caski cells are HPV-positive and express intermediate levels of EGFR and HER2, resembling typical CC tumours." (PMID 19654571, 2009). "Tumour phenotypes were analysed by immunohistochemistry on tissue microarrays using selected biomarkers (ER, PR, HER-2, EGFR, CK5/6, CK8, CK18)." (PMID 19589159, 2009). "It displays antitumor activity by directly inhibiting tumor cell proliferation and survival via EGFR and RET inhibition, as well as tumor angiogenesis via VEGFR inhibition." (PMID 19390592, 2009). "Tissue microarrays were constructed from the 279 available tumour specimens for each histological subtype and HER2 as well as EGFR status were assessed by FISH and IHC, respectively." (PMID 19088718, 2009). "Loss of VEGF expression was associated with more than a 4.3 times greater chance of complete tumour response compared with VEGF-positive tumours, while EGFR positivity resulted in a 5.78 times increased odds of complete tumour regression." (PMID 18182986, 2008). "A common phenomenon of tumour formation is the amplification of proto-oncogenes such as HER2, EGFR, CCND1, and c-MET, which provide a selective advantage for tumour cell growth and survival through overexpression." (PMID 18349818, 2008). "Aberrant activity of EGFR and HER-2/neu has been shown to be important in tumour growth and development." (PMID 18628764, 2008). "Simultaneous VEGF-positive and EGFR-negative expression was associated with a lack of complete tumour regression in more than 94% of cases and a 12-fold-decreased odds of response compared with EGFR-positive and VEGF-negative tumours." (PMID 18182986, 2008). "Marinkovich has demonstrated that the interaction of laminin-332 with α6β4 integrin and epidermal growth factor receptor (EGFR) was involved in promoting the PI3K activation and tumour invasion." (PMID 18283320, 2008).
tumor (continued). "Briefly, the interaction of laminin-332 with α6β4 integrin and EGFR is involved in promoting PI3K activation and tumour invasion." (PMID 18283320, 2008). "Positive staining was present in 6.2% of tumours for EGFR, 5.1% of tumours for HER-2/neu, 11.8% tumours for pEGFR, 100% of tumours for total AKT, 8.3% of tumours for pAKT and 36.9% of tumours for pERK." (PMID 18628764, 2008). "Furthermore, combining the uPAR down-regulation with EGFR inhibition showed a synergistic anti-tumor effect and might provide an alternative method to increase anti-proliferative effect of tyrosine kinase inhibitors with lower doses and duration to reduce their side effects during cancer control." (PMID 18519000, 2008). "Epidermal growth factor receptor (EGFR) is a receptor tyrosine kinase that is abnormally upregulated and activated in a variety of tumours." (PMID 18253126, 2008). "The degrees of staining with EGFR and VEGF antibodies were very similar to the degree of staining with Id-1 antibody and as tumour grade increased so did the degree of staining." (PMID 19014499, 2008). "Furthermore, increased sensitivity of ACCS-AS cells to anti-tumor effects of lower doses of tyrosine kinase inhibitors suggested that by inhibiting both EGFR and uPAR, we might achieve further goals by reducing unwanted side effects resulted from high doses of such agents." (PMID 18519000, 2008). "In contrast, EGFR, CCND1, and HER2 were amplified in 3.5–6.7% of tumours, often >9 times the normal copy number and frequently amplified in small amplicons indicative of the selective amplification of these genes." (PMID 18349818, 2008). "In agreement with previous large studies, we also show a relatively low percentage of EGFR- and HER-2/neu-overexpressing tumours." (PMID 18628764, 2008). "When these molecules are used in treatment, the pathways such as EGFR and VEGF contributing to tumour progression through different mechanisms will be kept under control by a single therapeutic agent." (PMID 19014499, 2008). "EGFR and HER2 are expressed in circulating tumor cells, but the activation status of downstream signaling molecules has not yet been reported." (PMID 18822183, 2008). "In the majority of studies, EGFR and K-RAS status was determined on the primary tumours and there are very few data concerning those of corresponding metastases." (PMID 19238633, 2008). "Following injection of the compound to U87MG.wt EGFR tumor-bearing mice (5 mg/kg i.v.), ML04 demonstrated significant inhibition of EGFR phosphorylation levels in tumors in vivo at different time points post administration." (PMID 18991714, 2008). "We first treated tumor-bearing C/L858R+T790M animals with either placebo or 17-AAG, sacrificed mice 6 hours later, and examined the levels of total EGFR in lung lysates." (PMID 17726540, 2007). "Growth factor receptors with tyrosine kinase activities such as EGFR, HER-2/neu, and c-Kit have recently emerged as promising targets for novel therapeutic agents, especially in some poorly chemosensitive neoplasms." (PMID 17876336, 2007). "Gefitinib treatment reduced EGFR phosphorylation at tyrosine 1068 and ERK phosphorylation in the RWGT2 tumours consistent with a blockade of EGFR kinase activity." (PMID 17533397, 2007). "In these models, an upregulation of the ERα-p-Ser118 following an activation of growth factor pathway signalling (EGFR, IGFR) and the activation of MAP kinase has been demonstrated when tumours started to grow despite letrozole." (PMID 17712311, 2007). "With regard to the expression of HER-2 and EGFR on oesophageal SCC, EGFR-positive tumours were observed in 35% of patients with oesophageal SCC, and HER-2-positive tumours were observed in 31% of them in the present study, in line with previous reports." (PMID 17622245, 2007). "An increasing body of evidence shows that HER3 plays a critical role in EGFR- and HER2-driven tumours." (PMID 17667926, 2007).